IL4 (interleukin 4)
Diseases named in the same sentence as IL4 in open-access papers (continued):
Sharing a sentence is not in itself a finding about the gene and the disease.
Allergy (continued). "The presence of allergic markers, such as elevated immunoglobulin E (IgE) levels and Th-2-driven cytokines (IL-4, IL-5), in the middle-ear effusions of patients with AR, strengthens the hypothesis that allergy-induced inflammation plays a role in OME pathogenesis." (PMID 40497981, 2025). "Thus, IL-4 and IL-4R might mediate allergic reactions by promoting the M2 polarization of macrophages." (PMID 40005151, 2025). "The inhibitory effects of Cd on the production of the Th1 signature cytokine IFN-γ and upregulation of the Th2 cytokine IL-4 (in response to Cd) may not only inhibit the generation of Th1 responses but could also potentially increase sensitivity to the development of allergies." (PMID 39199178, 2024). "Early life overexposure to IL-4, which can occur because of TH2 sensitization from allergic disease, has been reported to reduce myelination and lead to cognitive impairment and developmental delays, and these effects have been found to be inhibited with IL-4 neutralization." (PMID 38354043, 2024). "The literature reports that the reduction in the IL-4 cytokine can further decrease the expression of immunoglobulin E (IgE) levels after B cell activation, and the expression of IgE levels is mainly used clinically to reflect the severity of allergic reactions in the body." (PMID 39684557, 2024). "Similarly, during the allergy season, the levels of IL-4 and IL-10 decrease in nasal fluid." (PMID 37692890, 2023). "Contrary to what might have been predicted by the Th1-Th2 cytokine shift paradigm, infections with helminths result in a Th2-polarized immune response including production of IL-4, IL-5, IL-13, eosinophilia, and high serum titers of IgE, all hallmarks of allergic disease." (PMID 35648372, 2023). "Elevated IL-4 levels observed in the context of the knockout of ITK have been suggested to be linked to weaker Th2 responses and Th1 cell expansion in a manner that may contribute to certain parasitic infections and allergic diseases." (PMID 37266435, 2023). "Even though the effector mechanisms are not clearly identified, IgE antibody (antibody-dependent allergic reactions) and other allergy-related mediators including IL-4 cytokine might be involved in the pathogenesis of chemotherapy-related allergic manifestations." (PMID 35307016, 2022). "However, as IL-4 plays a major role regarding pre-GC B-cell priming and promotes class switch to IgG4 and IgE, studies focusing on, e.g., IgG4-related disease or allergy, might want to use IL-4 nonetheless." (PMID 35844625, 2022). "Additionally, neither percentages of eosinophils, or IgE-binding cells, nor frequencies of IL-4+ lymphocytes were increased in horses with sEA, contradicting an excessive type 2 immune response and allergy as the underlying pathogenesis mechanism of sEA." (PMID 35874777, 2022). "Furthermore, the IL-17A, IL-23, IFN-, IL-4, and IL-10 serum levels were also compared according to gender, antihistamine receiving, nose picking, bleeding of the gums, smoking, familial history of epistaxis, and clinical presentations similar to allergies." (PMID 35145935, 2022). "Indeed, studies continue to support basophils as key participants in IgE-mediated reactions, where they infiltrate inflammatory lesions, release pro-inflammatory mediators (histamine, leukotriene C4: LTC4) and regulatory cytokines (IL-4, IL-13) central to the pathogenesis of allergic diseases." (PMID 36578500, 2022). "At the same time, mouse serum OVA-sIgE, total IgE, IL-4, and IL-5 levels, along with H&E staining of nasal tissue, showed that gut microbiota dysbiosis dysregulates Th2 type allergic reaction and nasal inflammation in AR mice, which is consistent with previous studies of other allergic diseases." (PMID 36439824, 2022).
Allergy (continued). "Moreover, in the study, we investigated the changes in the Th2 cytokine profile–IL-4 (increased production in allergic reactions) and IL-6 (increased production in inflammatory reactions) in order to assess the influence of HBOT on the severity of inflammation in patients with AD." (PMID 33802050, 2021). "The association between LPP and allergy may be mediated by an effect on the expression of BCL6 (B cell lymphoma 6), a transcription factor that represses the STAT6-mediated response to IL-4 and IL-13 and IgE class switching and inhibits Th2 cell differentiation in a mouse model." (PMID 32082391, 2020). "Furthermore, an examination of the proportion of Th2 lymphocytes induced in the small intestinal lamina propria revealed that p.o. administration of C. koseri yielded an increased proportion of CD4+ IL-4+ lymphocytes (Th2 lymphocytes) in OVA-specific allergy mice." (PMID 31611274, 2019). "Although systemic administration of IL-4 and IL-10 was well tolerated, systemic exposure to IL4–10 FP upon leakage of the local compartment may result in undesirable side effects, such as an increased risk of developing allergy." (PMID 31879800, 2019). "Furthermore, the cytokines IL-4 and IL-13 can induce multiple fusogenic effects, which result in membrane fusion and giant cell formation and are responsible for the polarization of immunity towards Th2 response and IgE mediated allergy." (PMID 30941365, 2019). "Therefore, the IL-33/Bcl6 axis might participate in allergy pathology via the regulation of Il4 in MPT cells to promote disease development in MPTH2 and NAMTH2 cells, contributing to the maintenance and exacerbation of disease pathology." (PMID 29696026, 2018). "Thus, it is necessary to understand the different signaling responses and downstream effects of these two cytokines to rationally design inhibitors of the IL-4- and/or IL-13-induced responses that could be used as therapeutics for asthma and allergies." (PMID 29868002, 2018). "Therefore, environmental pollutants might lead to the occurrence of allergic diseases by altering methylation in the promoter regions of IFN-γ or IL-4, and aggravating Th1/Th2 imbalance." (PMID 29707116, 2018). "In animal models of allergy to Aspergillus through nasal route, we found that inhalation of diesel PM could alter DNA methylation levels of the two important genes IFN-γ and IL-4 in allergic diseases, thereby increasing the secretion of total IgE and resulting in disease onset." (PMID 29707116, 2018). "Thus, we may conclude that the high serum level of IL-4 may participate in the pathogenesis of PV, as IL-4 is involved in allergy and other immune system disorders." (PMID 29201111, 2017). "Therefore, some studies suggested that LAB strains capable of inhibiting IL-4 expression in vitro could perform an anti-allergy effect in vivo." (PMID 27764153, 2016). "In experimental studies on different models of allergic diseases, gallic acid is demonstrated to suppress of allergen induced hypersensitivity reactions in mice and inhibit release of histamine and helper T cell subtypes, IL-4, IL-5 and IL-2 form human mast cells." (PMID 27536321, 2016). "IL-4 along with IL-5 modulates eosinophil activation to stimulate B cells, IgE production, and mast cell degranulation and their reduction, has been shown in this study, could be involved in the modulation of symptoms of allergic disease." (PMID 25890178, 2015). "The involvement of Th2 cells both helps to explain the joint involvement of IgE-producing B cells (via IL-4 and IL-13), mast cells (via IL-4 and IL-10) and eosinophils (via IL-5) in the allergic inflammatory process and accounts for the other pathophysiologic features of allergy." (PMID 24624888, 2014).
Allergy (continued). "The involvement of Th2 cells both helps to explain the joint involvement of IgE-producing B cells (via IL-4 and IL-13), mast cells (via IL-4 and IL-10), and eosinophils (via IL-5) in the allergic inflammatory process and accounts for the other pathophysiologic features of allergies." (PMID 24707309, 2014). "Th2 cells are involved in all stages of immune response in the course of the allergic reaction, and studies carried out so far indicate that these cells are also the source of many proinflammatory cytokines and chemokines involved in allergic inflammation: IL-4, -5, -10, and -13." (PMID 23970818, 2013). "Vaccination strategies against Th2-related diseases, such as allergies or parasitic infections, should not only concentrate on inhibiting anti-inflammatory Th2 responses by inducing a strong Th1 phenotype, but need to consider the proinflammatory effect of IL-4 as adjuvant on the vaccine efficiency." (PMID 22802978, 2012). "Although we were unable to detect CMP-specific IgE, our findings about elevated serum IL-4 together with significantly higher CMP-specific IgG1 in CTL+ mice in comparison with CTL- mice indicate that IgE-mediated allergy may have occurred in CMP-sensitized mice." (PMID 22145744, 2011). "In the IP group of mice, both LGG1 and LGG2 groups, in comparison with CTL+ mice, may possibly alleviate allergy as indicated by numerically lower hypersensitivity responses, lower IL-4 levels, and lower CMP-specific IgG1 but higher IFN-γ and CMP-specific IgG2a levels." (PMID 22145744, 2011). "Since tryptase is a unique secretory product of mast cells and IL-4 is a classic Th2 cytokine which is actively involved in the pathogenesis of allergic reactions, induction of IL-4 release from mast cells by tryptase may suggest a self-amplification mechanism of allergic reactions." (PMID 19732468, 2009). "In allergy-related cytokines, Fat only led to significant increases in multiple BALF cytokines, notably IL-4, IL-5, IL-6, IL-12, IL-13, IL-17, IL-33, TNF-α, and IFN-γ, compared to the normal chow group (NC) (all P < 0.05 or P < 0.01)." (PMID 40998975, 2025). "IL-4 may use its α- chain in the early and later stages when B cells are isotype-switched to secrete IgE, while IL-13 uses this receptor to promote the production and development of airway hyperresponsiveness and inflammation in the late stage of the allergic reaction." (PMID 40953067, 2025). "Studies have shown that Th2-related cytokines such as IL-4, IL-5, and IL-13 can participate in the expression and secretion of mucin genes MUC5AC and MUC5B,29, 30, 31 further indicating the role of allergy in the occurrence and development of ETD." (PMID 38274710, 2024). "Analysis of the drug treatment groups revealed lower levels of serum total IgE, OVA-specific IgE, and Th2 cytokines, including IL-4, IL-5, IL-13, IFN-γ, and eosinophils, compared to the allergy group." (PMID 38396957, 2024). "The results suggest that the body weight and thymus index returned to normal levels; allergy scores, serum OVA-sIgE, IL-4, IL-5, and IL-10 expression decreased; and IFN-γ and IL-2 increased significantly in the ZW3 group compared with the allergy group." (PMID 39796306, 2024). "Damaged-epithelial cells-derived IL-25 and IL-33 rapidly induce secretion of IL-4 and IL-13 in ILC2 cells, indicating that ILC2 activation is induced in the early phase of allergy." (PMID 39567378, 2024). "Prednisolone influences IL-4 levels in pneumonitis, GRO-α levels in hypophysitis, and CTACK levels in allergic reactions, resulting in a slight further increase in the cytokine level for the respective irAE, compared to patients not receiving prednisolone." (PMID 39687621, 2024). "Likewise, IL-4 is primarily responsible for allergic inflammation and increased mucus production, which facilitates the differentiation of naïve T-helper cells into Th2 cells, contributing to the advancement of allergic diseases and promoting B cell maturation and the transition to IgE." (PMID 39594470, 2024).
Allergy (continued). "Cytokine recruitment, namely, IL-4, IL-5, IL-6, and TNF-α, encourages IgE synthesis in the first phases of an allergic reaction." (PMID 38835658, 2024). "A significantly smaller CD8+ iNKT cell population producing IFN-γ, IL-4, IL-5, and IL-10 in peanut-allergic adults was identified after exposure to DCs loaded with peanut oil, suggesting that despite a higher overall iNKT cell population, certain iNKT cell responses may be reduced in allergy." (PMID 38022648, 2023). "Any disruption of the cytokine secretion, especially increased IL4 and/or decreased IFNG, are considered to be a major factor contributing to allergy development." (PMID 37520545, 2023). "First, isolated MVs (without SAEW treatment) prepared in a mixed ratio of 1:0 were added to RBL-2H3 cells, and the mRNA expression levels of the allergy-related genes HDC, FcεR1α, IL-4, and TNF-α were examined." (PMID 38282743, 2023). "IL‐9 producing TH9 cells (CCR4− CCR6+ CCR10− CXCR3+) can be induced by the growth factor TGF‐β and IL‐4 from TH2 cells and are similarly involved in immunity against intestinal helminths and onset of allergies." (PMID 36740883, 2023). "They function mainly in the mediation of allergic disease, parasitic as well as helminthic infections, and participate in type 2 (TH2) inflammation that involves key cytokines such as IL-4, IL-5, and IL-13." (PMID 36832203, 2023). "In the OVA-induced ASA, repeated exposure to OVA induces allergic reactions that are enhanced by the production of OVA-specific IgE, IL-4, and histamine." (PMID 37296614, 2023). "In response to specific antigen challenge, FA mice showed diarrhea, drop of the core temperature, increase in serum specific IgE, and allergy-related cytokines, including MCP1, EPX, and IL-4, in gut lavage fluids (GLF)." (PMID 35096267, 2022). "The cytokine release of IL-4, IL-10, and IFN-γ was then determined via quantitative equine capture ELISA (R&D systems, Minneapolis, MN, USA) in order to detect an allergy-mediated Th2 immune response (IL-4) and/or a proinflammatory Th1 response (IFN-γ)." (PMID 36009677, 2022). "In the allergy-induced group, the mRNA expression of IFN-γ and IL-12 was reduced, and the expression of IL-4 and IL-13 was significantly increased after treatment with anti-DNP IgE." (PMID 35889810, 2022). "The potential IL-4-inducing peptide segments on VP2 of BTV2 (allergy reported) and BTV12 (non-allergy reported) were synthesized to test for their ability to induce IL-4 in bovine PBMCs." (PMID 33375108, 2020). "Here, both the beclomethasone group and the CpGsd group could achieve a significant reduction of the IL‐4 concentration directly after treatment, analogous to the results of a study by Giguere, in which an inhalative fluticasone therapy also effected a decrease in the allergy‐mediating Th2 cytokine." (PMID 31141308, 2019). "Specifically, the introduction of specific pathogen free (SPF) bacteria into germfree (GF) mice has been shown to result in lower concentrations of interleukin 4 (IL-4), IL-5 and eosinophil numbers in an OVA-induced allergy model." (PMID 30899257, 2019). "But additional discrete T helper cell subsets are involved in human allergy; Th9 cells, induced by TGF‐β and IL‐4, secrete IL‐9 which enhances the growth of mast cells, and can lead to inflammation in the lung and intestines, including intestinal anaphylaxis." (PMID 29164823, 2018). "Bcl6 is a critical regulator of IL-4 production by MPT and MPTH2 cells in TH2 immune responses related to the pathogenesis of allergies." (PMID 29696026, 2018). "The results showed that IFN-γ level was significantly higher (p < 0.05), while IL-4 and IL-10 levels were significantly lower in the control and FOS groups compared with the allergy group (p < 0.05)." (PMID 30524396, 2018). "Mediators such as cytokines (IL-4, TNF-α, etc.)from the cells are involved in the late phase reaction of allergy." (PMID 30618741, 2018).
Allergy (continued). "The markers of inflammation and allergic reaction, IFN-γ, TNF-α, IL-4, and IL-6, were suppressed, especially after treatment with 100 μg/mL ST." (PMID 29849717, 2018). "Since IFN-γ exerts a direct inhibitory effect on Th2 cytokines and reduces IL-4 and IL-5 production levels, IFN-γ secreted from Th1 cells inhibits the Th2 response leading to allergic disease." (PMID 30545126, 2018). "After the experiment, the levels of IgE, IL-4, and IFN-γ in the serum were measured to estimate the modulating action of Shenqi on allergic reactions." (PMID 28327534, 2017). "In a recent meta-analysis of allergy related cytokines in depression, IL1, IL4, IL6, and TNF-α, were found increased in depression compared to nondepressive study subjects and were considered to be a possible inflammatory link between the two disorders." (PMID 26783384, 2015). "DEHP is also considered to promote a deviation of Th2 response (related to allergy) by suppressing IFN-α/IFN-β gene expression and by modulating interleukin 4 (IL-4) and immunoglobulin E (IgE) production." (PMID 25960783, 2015). "In a study of macrophages in lung inflammation, mir-124 expression was up regulated in macrophages by IL4 and IL13 stimulation as well as by allergy induced inflammation." (PMID 26222688, 2015). "For example, miR-21 upregulates IL-12 in the airway during an allergic reaction by binding to IL-12p35 and increasing interferon (IFN)-γ expression, which in turn downregulates IL-4 and promotes a Th1 bias." (PMID 26418311, 2015). "IL-1, IL-6 and TNF-α are the main Th1-type cytokines associated with dry eye syndrome, while the inflammatory Th2-type cytokines IL-4, IL-5 and IFN-γ tend to be increased in allergic diseases." (PMID 26588473, 2015). "The anti-inflammatory effects of mapracorat were determined after allergy-related chemokine/cytokine release and ICAM-1 was induced with IL-4 plus TNF-α in HConEpiC." (PMID 23878502, 2013). "The multiple linear regression analysis showed that after Derp 1 specific stimulation, allergy (R + AR) correlated positively with percentages of ICOS, IL-13 and IL-4-expressing T cells and negatively with CTLA-4 and IL-10-expressing T cells." (PMID 21356099, 2011). "Recent work shows the presence of a local allergy reaction in acute phlegmonous appendicitis (APA), with an elevation of Th2 cytokines IL-4, IL-5, and IL-9 in appendicular lavage fluid (ALF), a new concept for evaluating the local immune response in AA developed by our group." (PMID 41596388, 2026). "The Th1/Th2 paradigm in adult allergic disease seems not to be applied in infants, where a stronger Th1 and Th2 bias has been demonstrated, with deficient production of IFN‐γ, IL‐4, and IL‐17A." (PMID 40952045, 2026). "For instance, IL4, IL13 IL10, and IFN-γ, which are anti-inflammatory/regulatory cytokines, can modulate inflammatory processes like allergies and intestinal inflammatory diseases by regulating the immune response of the T helper 2 cells (Th2) and the T helper 1 responses (Th1)." (PMID 39891859, 2025). "Currently available IL-4-, IL-5-, and IL-13-targeted therapies underscore the translational gap between the established indication in allergic diseases and the lack of clinical evidence in obesity." (PMID 41007770, 2025). "The blocking of IL-4 or downregulation of IL-4R exerted negative effects on the hallmarks of allergic reactions in vitro." (PMID 40005151, 2025). "In turn, the histamine increases the secretion of Th2 cytokines such as IL-4, IL-5, and IL-13 and inhibits the production of the Th1 cytokines IL-2 and IFN-γ through the upregulation of prostaglandin E2 and nitric oxide, thereby exacerbating the allergy." (PMID 39403377, 2024). "Consensus was achieved on several statements related to the indication for biologics in patients with UAD, such as the use of anti-IL-4/IL-13 or anti-IgE regardless of the presence of allergy (M: 8), although the level of agreement was lower among allergists." (PMID 37088840, 2023).